KRAS (KRas proto-oncogene, GTPase)
Diseases named in the same sentence as KRAS in open-access papers (continued):
Sharing a sentence is not in itself a finding about the gene and the disease.
biliary tract cancer (26 papers, 2011 to 2026). "•Using data from >7000 biliary tract cancers, we examined the link between KRAS variants and prognosis/treatment outcomes." (PMID 40499463, 2025). "•In patients with biliary tract cancer, KRAS variants were significantly associated with poor prognosis." (PMID 40499463, 2025). "In addition to these tumors, KRAS G12C mutations are also found in smaller proportions of other solid tumors, such as endometrial cancer and biliary tract cancers." (PMID 40940900, 2025). "•KRAS variants were associated with poor treatment outcomes in patients with biliary tract cancer." (PMID 40499463, 2025). "•KRAS variants may be potential prognostic and predictive markers for survival/treatment outcomes in biliary tract cancers." (PMID 40499463, 2025). "With respect to the MAPK axis, population-level genomics place frequent activation via upstream lesions (e.g., KRAS) across biliary tract cancers, reinforcing the centrality of RAS–RAF–MEK–ERK signaling." (PMID 41373405, 2025). "We previously established mouse models of biliary tract cancer (BTC) based on the injection of cells with biliary epithelial stem cell properties derived from KRAS(G12V)-expressing organoids into syngeneic mice." (PMID 36551889, 2022). "In a phase I/II basket trial (NCT03785249) of KRAS G12C inhibitor adagrasib, 42 patients with KRAS G12C positive gastrointestinal cancers including eight biliary tract cancer cases were enrolled in a phase II cohort." (PMID 36290850, 2022). "KRAS G12C was identified in 0.6% (11/1573) of patients with biliary tract cancer registered in cBioPortal." (PMID 36290850, 2022). "Occasional instances of NTRK1-3 rearrangements were reported in KRAS mutation-negative pancreatic carcinomas and biliary tract cancers." (PMID 38612902, 2024). "Beyond NSCLC and CRC, KRAS G12C inhibitors were also tested in other solid tumors, particularly in PDAC and biliary tract cancers (BTCs)." (PMID 40940900, 2025).
biliary tract cancer (continued). "At this time (as of September 2022), there are no molecularly targeted therapy recommendations for KRAS G12C positive biliary tract cancer in NCCN guidelines." (PMID 36290850, 2022). "However, this study focused exclusively on ICC, rather than on biliary tract cancer, contributing to a better understating of KRAS-related molecular biology." (PMID 29642912, 2018). "Furthermore, the expression status of various key molecular targets, such as KRAS, B-raf and MEK, should be examined to identify patients with biliary tract cancer who may benefit from treatment with anti-EGFR monoclonal antibody." (PMID 24212807, 2011).
papillary thyroid cancer (26 papers, 2012 to 2025). "KRAS mutation was found in 52.6% of follicular carcinomas and 47.4% of papillary thyroid carcinomas." (PMID 36510281, 2022). "In Part A, there was one partial response (PR), in a patient with V600E BRAF-mutated papillary thyroid cancer (KRAS-WT, PTEN weakly reactive) receiving E6201 480 mg/m2, who had a response for four cycles." (PMID 29867224, 2018). "During dose escalation, a PR was observed in a patient with BRAF-mutated papillary thyroid cancer (KRAS-WT) receiving E6201 480 mg/m2 once-weekly." (PMID 29867224, 2018). "RET/PTC rearrangement, BRAF, NRAS, and KRAS mutations are considered to be mutually exclusive in papillary thyroid carcinoma." (PMID 28493027, 2017). "We analyzed mutation status of BRAF and RAS (HRAS, NRAS, and KRAS) oncogenes in 34 papillary thyroid cancer samples using MALDI-TOF-MS." (PMID 24367375, 2013). "The aim of this study was to investigate the relationship between the presence of the BRAF, HRAS, NRAS, and KRAS gene mutations and the development of dedifferentiation (iodine-refractory disease) and extrathyroidal disease in patients with differentiated thyroid carcinoma (DTC)." (PMID 40104288, 2025). "Notably we also identified one papillary thyroid carcinoma of follicular variant with both KRAS and EGFR mutation." (PMID 36510281, 2022). "This study was designed with the aim of examining the relationship between clinicopathological characteristics and mutations in the BRAF, HRAS, KRAS, and NRAS genes with metastatic disease and RAIR development in patients with differentiated thyroid cancer." (PMID 40104288, 2025). "In comparison, BRAF p.V600E occurs in over 50% of adult papillary thyroid carcinoma (PTC) and NRAS/HRAS/KRAS mutations in 30-45% of follicular thyroid cancer and follicular variant PTC." (PMID 39558957, 2024). "BRAFV600E, KRAS variants, NRAS variants, and HRAS variants have also been observed in papillary carcinoma originating from struma ovarii." (PMID 36975488, 2023). "In COSMIC, KRAS G12D and G12V are reported to occur in only 0.6% and 0.2% of papillary thyroid carcinomas but were detected in 88.2.0% and 58.8% of papillary thyroid carcinomas analyzed by ACB‐PCR, respectively." (PMID 31469467, 2020). "Mutations of BRAF, KRAS, and NRAS were tested in tissue samples of 53 patients (39 papillary thyroid cancers, 10 with follicular variant; 3 follicular thyroid cancers, 1 oxyphilic variant)." (PMID 28493027, 2017). "Although only one patient with an indeterminate lesion on thyroid cytology showed KRAS mutation (codon 146) in the preoperative plasma, that KRAS mutation was not identified in the stage I papillary thyroid carcinoma tissue." (PMID 33915745, 2021). "All papillary carcinomas were associated with mutated KRAS and lacked mutated GNAS18, irrespective of the presence of an associated IPMN." (PMID 28145465, 2017). "Claudin-10 (CLDN10) has been reported to be upregulated in papillary thyroid cancer and KRAS mutant non-squamous cell lung cancer and reduced in clear cell renal cell carcinoma." (PMID 38540693, 2024). "While not as extensively validated as the KRAS-variant, another SNP in the 3′ UTR of KRAS, the rs712 variant, is being assayed as a biomarker for risk of oral squamous cell carcinoma, gastric, colorectal and papillary thyroid cancer." (PMID 25433809, 2014).
adenomyosis (25 papers, 2019 to 2026). The growth of endometrial tissue inside the muscular wall of the uterine corpus. "KRAS mutations have been reported to be predominant in adenomyosis, but mutations in other cancer-associated genes, such as PIK3CA, were rare." (PMID 40679511, 2025). "The frequency of KRAS mutations per sample was 34%, which is generally consistent with the previous report, verifying KRAS mutation as a major driver of adenomyosis." (PMID 40679511, 2025). "KRAS (G12/G13) mutation or variant allele frequency was significantly higher in endometrial tissues of adenomyosis patients compared with disease-free patients." (PMID 40590223, 2025). "The proliferation of adenomyosis is associated with the MAPK signaling pathway and genetic variations, among which the activating mutation of KRAS is the most common genetic variation in adenomyosis epithelial cells." (PMID 41278208, 2025). "For instance, the same somatic mutations in the KRAS gene mutation can be detected in both adenomyosis and the corresponding eutopic endometrium, suggesting a clonal relationship." (PMID 39903727, 2025). "It subsequently acquired a KRAS p.G12D mutation and gave rise to a subclone (cluster 3) that was unique to one of the three adenomyosis samples (A1)." (PMID 40679511, 2025). "On the other hand, most adenomyosis cases where mutations were shared among multiple lesions had either a KRAS mutation or chr1q gain as the ancestral clone." (PMID 40679511, 2025). "In adenomyosis, the most frequently mutated genes included KRAS (34.1%), PIK3CA (12.2%), ARID1A (12.1%), and FBXW7 (9.8%)." (PMID 40679511, 2025). "The MAFs of representative cancer-associated genes in adenomyosis exceeded 0.25, with KRAS and PIK3CA showing averages of 0.42 and 0.43, respectively, indicating their clonal expansion in adenomyotic lesions." (PMID 40679511, 2025). "Second-generation gene sequencing (NGS) indicates that adenomyosis is a condition associated with mutations in the KRAS gene." (PMID 39595579, 2024). "In adenomyosis, the theory of the invagination of glands into the myometrium is supported by the occurrence of KRAS mutations in the adjacent basal layer of the endometrium." (PMID 39595092, 2024). "The detection of mutations primarily in the KRAS (Kirsten Rat Sarcoma virus) genes in cases of adenomyosis highlights the significant role of these genes in the genetic pathogenesis of the disease." (PMID 39200389, 2024). "The identification of KRAS gene mutations in adenomyosis challenges the recent theory that molecular abnormalities in adenomyosis are primarily epigenetic or linked to abnormal gene expression." (PMID 39200389, 2024). "For example, there is increasing evidence concerning the role of KRAS mutations in the pathogenesis of adenomyosis." (PMID 37834773, 2023). "The finding of KRAS somatic mutations in 40% of adenomyotic tissue cells suggests that adenomyosis harbors signs of genomic instability." (PMID 36515351, 2022). "Mutations found in adenomyosis almost exclusively affected the KRAS gene and similar KRAS mutated gene was frequently identified in the epithelial cells of endometriotic lesions, whereas PIK3CA is the most mutated gene in eutopic endometrial cells." (PMID 35887822, 2022). "As an important finding, KRAS mutations are observed in not only adenomyosis lesions but also histologically normal endometrial tissues." (PMID 35203298, 2022). "It was shown that a KRAS mutation at the location of G12, which is well-known as an oncogenic mutation, is the highest alteration (~37%) in adenomyosis." (PMID 35203298, 2022). "Recurrent somatic pathogenic KRAS mutations, including 25 cases of alterations at G12 and 1 case at Q61, were identified in 37.1% (26/70) of adenomyosis cases." (PMID 31857578, 2019). "Our data collectively raise the possibility that KRAS-mutated clones arising in NE acquire enhanced invasiveness and proliferative capacity that enable them to grow ectopically, driving adenomyosis." (PMID 31857578, 2019).
adenomyosis (continued). "However, in this study, we focused on the genomic analysis of normal endometrium limited to the cases of adenomyosis, KRAS mutations tended to be more frequent than PIK3CA mutations." (PMID 40679511, 2025). "Additionally, KRAS mutations were reported to be more frequent in the endometrium of patients with co-existing adenomyosis–endometriosis patients than in adenomyosis alone." (PMID 41272701, 2025). "In addition, three subjects harbored identical KRAS mutations shared between adenomyosis and uterine endometrium (subjects 2, 5, and 6), with one subject also sharing a PIK3CA mutation between these tissues." (PMID 40679511, 2025). "For example, cases with adenomyosis could harbor KRAS mutations in their normal endometrial glands more frequently than those without adenomyosis." (PMID 40679511, 2025). "KRAS mutations have been found in endometrial carcinomas and adenomyosis." (PMID 36291839, 2022). "The fact that adenomyosis originates from the basalis endometrium is based on the targeted deep sequencing analysis of epithelial cells in adenomyosis and adjacent basalis endometrial glands that demonstrates recurring KRAS mutations in both cell types." (PMID 35887822, 2022). "Based on these NGS data, it is tempting to assume that once trapped within the myometrium during traumatic processes at the endometrial-myometrial junction, adenomyosis primarily stems from the basalis portions of the endometrial glands that harbor a KRAS mutation." (PMID 35887822, 2022). "Therefore, the authors conclude that adenomyosis etiology is strongly associated with KRAS mutations in the endometrium, as well as the status of KRAS mutations is likely to be a critical factor in selecting effective medical treatments." (PMID 35203298, 2022). "Somatic KRAS mutation is a critical genomic alteration associated with adenomyosis." (PMID 35887822, 2022). "Moreover, targeted deep sequencing analyses of epithelial cells demonstrated recurring KRAS mutations in both adenomyosis and eutopic basalis endometrial glands." (PMID 34681634, 2021). "They considered that KRAS-mutated adenomyosis clones originate from the eutopic normal endometrium." (PMID 34442357, 2021). "In any case, at least for oral DNG therapy, KRAS status may be a biomarker of treatment efficacy, and testing a needle biopsy of an adenomyosis lesion for KRAS mutation and/or PR expression might be a valuable diagnostic option." (PMID 31857578, 2019). "Based on these findings, we hypothesized that somatic KRAS mutation might be an important genomic alteration associated with adenomyosis." (PMID 31857578, 2019). "Taken together, these genomic analyses of NE suggest that an increase in expanded KRAS-mutated clones in this tissue may be an early step in the molecular pathogenesis of adenomyosis." (PMID 31857578, 2019). "Follow-up in a suitably large number of additional patient samples is required, but if corroborated, the latter result suggests our hypothesis that an increase in the frequency of KRAS-mutated clones in NE might be the origin of adenomyosis." (PMID 31857578, 2019). "DNG is a PR agonist, which prompted us to examine PR protein levels in KRAS-mutated adenomyosis." (PMID 31857578, 2019). "Thus, frequent KRAS mutations in the normal endometrium might initiate invasive and proliferative cellular functions to develop ectopic adenomyosis." (PMID 35203298, 2022). "Importantly, KRAS mutations have been found to be significantly high in adenomyosis lesions from the patients who have been treated with dienogest (an oral progestin, 84%) but do not respond well and eventually underwent hysterectomy compared with the patients without dienogest (26%)." (PMID 35203298, 2022). "In addition, a needle biopsy of an adenomyosis lesion with the assessment of KRAS mutation status and/or PR expression might be a valuable diagnostic possibility and, in future, in the case of KRAS-mutated lesion genetically guided therapy." (PMID 35206475, 2022).